SLC1A6 (solute carrier family 1 member 6)
Description:
Sodium-dependent, high-affinity amino acid transporter that mediates the uptake of L-glutamate and also L-aspartate and D-aspartate. Functions as a symporter that transports one amino acid molecule together with two or three Na(+) ions and one proton, in parallel with the counter-transport of one K(+) ion. Mediates Cl(-) flux that is not coupled to amino acid transport; this avoids the accumulation of negative charges due to aspartate and Na(+) symport. Plays a redundant role in the rapid removal of released glutamate from the synaptic cleft, which is essential for terminating the postsynaptic action of glutamate (Probable).
Synonyms: EAAT4
Tractability: Small molecule: it belongs to a druggable protein family. Antibody: UniProt places it where antibodies can reach, with high confidence; its Gene Ontology location is reachable by antibodies, with high confidence; UniProt predicts a signal peptide or a membrane-spanning region; the Human Protein Atlas places it where antibodies can reach. PROTAC: ubiquitination databases record sites on it; its protein half-life has been measured.
Gene: Protein-coding gene on chromosome 19 (14,950,033 to 15,022,990, reverse strand). Ensembl gene ENSG00000105143.
Subcellular location: Cell membrane
Subcellular location (Human Protein Atlas): Plasma membrane; Intermediate filaments
Pathways (Reactome):
Neuronal System: Glutamate Neurotransmitter Release Cycle
Transport of small molecules: SLC-mediated transport of amino acids
Gene Ontology:
Molecular function: glutamate:sodium symporter activity; L-aspartate transmembrane transporter activity; L-glutamate transmembrane transporter activity; high-affinity L-glutamate transmembrane transporter activity; neutral L-amino acid transmembrane transporter activity; symporter activity
Biological process: L-aspartate import across plasma membrane; L-glutamate import across plasma membrane; neurotransmitter uptake; amino acid transport; aspartate transmembrane transport; chemical synaptic transmission; L-glutamate transmembrane transport; neurotransmitter transport; import into cell; neutral amino acid transport
Cellular component: plasma membrane; membrane; membrane protein complex; glutamatergic synapse; Golgi apparatus; presynaptic membrane
Genetic constraint (gnomAD): Loss-of-function variants: 15 observed, 40.13 expected, observed/expected ratio (o/e) 0.37, 90% interval 0.25 to 0.58. The upper end of that interval is the gene's LOEUF score, 0.58, which puts it in group 2 of 6, group 1 being the genes least tolerant of losing a copy. Missense variants: 542 observed, 791.46 expected, observed/expected ratio (o/e) 0.68, 90% interval 0.64 to 0.74. Synonymous variants: 317 observed, 329.49 expected, observed/expected ratio (o/e) 0.96, 90% interval 0.88 to 1.06.
Homologues: Orthologues: chimpanzee SLC1A6 (99% identical), macaque SLC1A6 (98% identical), dog SLC1A6 (97% identical), pig SLC1A6 (97% identical), rabbit SLC1A6 (96% identical), mouse Slc1a6 (95% identical), rat Slc1a6 (95% identical), guinea pig SLC1A6 (93% identical), tropical clawed frog slc1a6 (69% identical), zebrafish slc1a6 (65% identical). Paralogues in human: SLC1A3 (65% identical), SLC1A1 (47% identical), SLC1A7 (46% identical), SLC1A2 (44% identical), SLC1A4 (41% identical), SLC1A5 (39% identical).
Diseases named in the same sentence as SLC1A6 in open-access papers:
SLC1A6 is named in the same sentence as 22 diseases in open-access papers, as found by Europe PMC text mining. Sharing a sentence is not in itself a finding about the gene and the disease. The quoted sentences say what the papers report.
nasopharyngeal carcinoma (2 papers, 2021 to 2022). A carcinoma arising from the nasopharyngeal epithelium. "On the other hand, an RNA sequence analysis showed that SLC1A6 (EAAT4) was upregulated in nasopharyngeal carcinoma cell lines resistant to radiation and with low sensitivity to cisplatin." (PMID 36457557, 2022).
Obesity (2 papers, 2019 to 2020). Accumulation of substantial excess body fat. "In addition, the m6A methylation levels of genes related to these diseases also changed after DBS; such changes occurred with Slc1a6 (an OCD-associated gene: hypermethylation), Kcnj11 (an obesity-associated gene: hypermethylation), and Dusp1 (an addiction-associated gene: hypermethylation)." (PMID 33343932, 2020).
schizophrenia (2 papers, 2008 to 2021). A major psychotic disorder characterized by abnormalities in the perception or expression of reality. "Recently, we have reported the positive association of SLC1A2 and SLC1A6, the genes encoding EAAT2 and EAAT4, respectively with schizophrenia, providing support for the potential important roles of EAATs in schizophrenia." (PMID 18638388, 2008).
ethanol abuse (1 paper, 2020). "It has been reported that only SLC1A6 and PCSK9 were associated with MA and/or ethanol abuse." (PMID 33192735, 2020).
gestational diabetes (1 paper, 2022). Carbohydrate intolerance first diagnosed during pregnancy. "Amino acid transporters such as SLC1A6 are vital for fetal growth with their expression likely being controlled by methylation which is altered in conditions such as gestational diabetes or PE." (PMID 35484822, 2022).
kidney cancer (1 paper, 2021). Primary or metastatic malignant neoplasm involving the kidney. "Additional examples among the core CT genes are CMTM1 (signaling molecule) and SLC1A6 (amino acid transporter), which are unfavorable expression markers for pancreatic and urothelial cancer, while KHDRBS3 (RNA splicing) and GLUD2 (glutamate dehydrogenase) are favorable markers for kidney cancer." (PMID 33426787, 2021).
lymph node metastasis (1 paper, 2023). "Therefore, it is speculated that AKAP7 and SLC1A6 play an important role in the occurrence of BLCA and lymph node metastasis." (PMID 37123010, 2023).
major depression disorders (1 paper, 2017). "SLC1A6, which is highly expressed in the cerebellum of human brain compared to other regions, showed lower levels of expression in prior studies of mood disorder diseases such as bipolar and major depression disorders in the striatum in situ hybridization study." (PMID 28166718, 2017).
tumor (3 papers, 2021 to 2025). "In contrast, SLC7A7 and SLC24A4 exhibit a more widespread expression in TAMs, while SLC1A6 was detected in only a small fraction of tumour cells." (PMID 38687049, 2024). "The mRNA expression levels of AHNAK, EMP1, RASGRP4, and HSPA1L were significantly down-regulated in BUC tumor tissues compared with normal tissues while SLC1A6 and PRSS8 were significantly up-regulated (P < 0.05)." (PMID 34905506, 2021). "The high expression of SLC1A6 in BLC and its association with poor prognosis suggest it may fuel aggressive tumor behavior." (PMID 41346448, 2025). "Interestingly, similar to the results obtained from bulk analysis, the single‐cell data showed a higher detection of SLC43A3, SLC2A10, SLC25A43, SLC7A7 and SLC47A1, which are highly expressed in tumour tissues, relative to SLC1A6 and SLC24A4, which are lowly expressed." (PMID 38687049, 2024). "Multivariate Cox regression analysis in the TCGA-BLCA dataset revealed that the expression levels of EMP1, RASGRP4, AHNAK, SLC1A6, and PRSS8 in tumor tissues were independent predictors for the unfavorable prognosis of BUC patients." (PMID 34905506, 2021). "The results demonstrated significantly higher expression of SLC43A3 and SLC2A10 in tumour slices compared to adjacent non‐cancerous tissue slice, with almost no detectable expression of SLC1A6 in the tumour slices." (PMID 38687049, 2024).
cancer (2 papers, 2021 to 2023). A tumor composed of atypical neoplastic, often pleomorphic cells that invade other tissues. "In this study, EFEMP1, LAMA2 and SLC1A6 were differentially expressed not only in N0 and N1–N3 groups, but also in cancer and paracancerous groups." (PMID 37123010, 2023). "SLC1A6 was highly expressed in BLCA cancer samples and also in N1–N3 samples." (PMID 37123010, 2023). "Compared with paracancerous tissues, AKAP7, EFEMP1, EPN2 and LAMA2 were lowly expressed in cancer tissues, while RPS6KA1, SLC1A6, TRABD and ZNRD1 were highly expressed in cancer tissues." (PMID 37123010, 2023). "To further validate the prognostic role of the SLC1A6 in NPC patients, we collected 78 biopsies from NPC patients in Sun Yat-sen University Cancer Center." (PMID 33927617, 2021). "Although the role of SLC1A6 in cancers was not well documented, other members of the SLC1A family were reported to be overexpressed in multiple tumors and predict poor prognosis." (PMID 33927617, 2021).
SLC1A6 also shares sentences with these, for which no sentence is quoted: Ataxia (4 papers); brain ischemia (2); cerebral infarction (2); glioma (2); spinocerebellar ataxia type 5 (2); cerebellar ataxia (1); infection (1); injury (1); mood disorder (1); nervous system diseases (1); prostate carcinoma (1); type II diabetes (1).